HMGB1 (high mobility group box 1)
Diseases named in the same sentence as HMGB1 in open-access papers (continued):
Sharing a sentence is not in itself a finding about the gene and the disease.
cancer (continued). "However, a systematic, comprehensive pan‐cancer analysis of HMGB1 in human cancers remains to be reported." (PMID 35765707, 2022). "However, T-reg cells secrete HMGB1, which promotes dendritic cells, and both HMGB1 and dendritic cells promote helper T-cells, which help promote cytotoxic cells that kill cancer cells." (PMID 36294824, 2022). "Moreover, HMGB1 has been demonstrated to play a critical role in the carcinogenesis of various cancer types such as esophageal squamous cell carcinoma, lung cancer, and liver tumors." (PMID 35562734, 2022). "Ecto-CRT, secreted ATP and released HMGB1 are vital for cancer cell ICD." (PMID 36057637, 2022). "On the other hand, another type of neutrophils called N2 neutrophils appear to be tightly involved in cancer progression through the active formation of neutrophil extracellular traps (NETs), which release abundant HMGB1 extracellularly as well as S100A8/A9 and our unpublished data." (PMID 36142212, 2022). "Furthermore, HMGB1 was identified as a promoting molecule coming from cancer cells to boost the transition process toward NETs." (PMID 36012397, 2022). "A DAMP, HMGB1 is actively secreted by immunocompetent cells or passively released from apoptotic necrotic cells, which activates the immune response and promotes inflammation and cancer development." (PMID 35911735, 2022). "In addition, ferroptosis induced by photodynamic therapy (PDT) promoted the release of HMGB1/ATP from cancer cells and the subsequent phagocytosis by macrophages and activation and maturation of BMDCs." (PMID 36317423, 2022). "The activations of recruited CAFs, TAMs, and MDSCs in the TME by various factors, including HMGB1, are important physiological barriers for penetrating T and NK cells through the release of immunosuppressive cytokines and chemokines, thus making cancer cells escape from immunosurveillance." (PMID 35408786, 2022). "Indeed, the downregulation of Vanguard and ensuing changes in HMGB1 localization proved a liability with respect to perturbing DNA repair and impacting cancer cell growth and survival." (PMID 36047643, 2022). "Additionally, HMGB1 and PD-L1 expression of cancer cells were observed in the treatment of ferroptosis + NK cells." (PMID 36175895, 2022). "C5a enhances PMN-MDSC migration and invasion and, together with the costimulatory factor nuclear protein high mobility group box 1 (HMGB1) produced by cancer cells, induces the formation of NETs that in turn promote cancer cell dissemination and lung metastasis." (PMID 36003145, 2022). "However, more in-depth exploration is required regarding how HMGB1 affects cancer progression through its participation in DNA damage repair." (PMID 35637945, 2022). "In conclusion, this study investigates the genetic variation of HMGB1 in human malignant tumours." (PMID 35765707, 2022). "When necroptotic cancer cells are used as a vaccine to protect mice against subsequent challenge with viable cancer cells, they release DAMPs such as HMGB1 and ATP and can induce activation and maturation of bone-marrow derived dendritic cells in vitro and in vivo." (PMID 35844506, 2022). "Pharmacological inhibition or shRNA-mediated depletion of STAT3 suppressed the NDV/FMW-caused ICD determinants, including HMGB1 and HSP70/90 release, CRT exposure, and ATP secretion, suggesting plausible mechanisms to fine-tune NDV-induced ICD in diverse cancer types." (PMID 36755812, 2022). "In this work, we investigated whether the deletion of the C-terminal tail of HMGB1 might affect its anticancer activity as well as its effect on the metabolism of cancer cells." (PMID 35887213, 2022). "In addition, studies also showed that HMGB1 release serves as the marker of immunogenic cell death, and induces the cytotoxic T immune response to cancer by activating antigen-presenting dendritic cells." (PMID 36267972, 2022).
cancer (continued). "After the occurrence of immunogenic cell death of cancer cells, danger-associated molecular patterns (DAMPs), such as HSP70, ATP secretion, cytochrome c release, and HMGB1 protein, could be induced." (PMID 35625834, 2022). "Also, the usefulness of the serum HMGB1 as a potential biomarker was evaluated and the cut-off value of serum HMGB1 level was 4.80 ng/ml, the sensitivity and specificity in cancer identification were respectively 42.3% and 92.0%." (PMID 35462765, 2022). "Despite its complexity, the role of HMGB1 in cancer is unquestionable." (PMID 33628090, 2021). "The anticancer immune response of ICD is contributed by the release of damage-associated molecular pattern molecules (DAMPs) by dying cancer cells and stressed cancer cells, such as high-mobility group box 1 (HMGB1), heat shock protein 70 (Hsp70), ATP, annexin A1 (ANXA1), and calreticulin (CRT)." (PMID 33799527, 2021). "HMGB1 is involved in cancer angiogenesis and in cancer progression and metastasis development." (PMID 34305932, 2021). "The paradoxical roles of HMGB1 in cancer have been of interest to many researchers over the years." (PMID 34721407, 2021). "Using K562-differentiated megakaryocytes and murine platelets, conditioned medium and exosomes obtained from megakaryocytes and platelets contained high-mobility group box 1 (HMGB1) and promoted cancer cell survival, as well as protected cancer cells from doxorubicin cytotoxicity." (PMID 33669632, 2021). "Together, these data suggest that HMGB1 has a role in ribosome biogenesis through interaction with and regulation of expression of genes involved in this process, with significant clinical impact in cancer patients." (PMID 34572914, 2021). "An interesting study assessed EMT, HMGB1 and NETs in cancer." (PMID 34758877, 2021). "HMGB1 is involved in various diseases, including cancer and senescence." (PMID 33558529, 2021). "In addition, HMGB1 release was observed in cancer and immune cells where this process can be triggered by various endogenous as well as exogenous stimuli." (PMID 34234778, 2021). "The existing evidence clearly suggests that high-mobility group box 1 (HMGB1) has different potentials in cancer progressions such as mounting the growth, angiogenesis, migration, invasion, metastasis, and inhibition of apoptosis by affecting different signaling pathways." (PMID 34249257, 2021). "Glycated HMGB1 attracts attention as a molecule with new bioactivity and might be a marker for cancer malignancy or a new therapeutic target." (PMID 34068442, 2021). "Additionally, accumulating evidences suggests that high HMGB1 expression is closely related to the development and progression of cancer through its important functions in promoting proliferation, invasion and migration 13-15." (PMID 33628090, 2021). "Several HMGB1-targeting agents have been developed and used in experimental cancer research." (PMID 34257571, 2021). "Therefore, exosomes and exosomal HMGB1 appear to have roles in platelet-driven cancer malignancy and represent targets of antiplatelet drugs in anticancer treatment." (PMID 33669632, 2021). "In our previous study, we identified HMGB1 as a critical determinant of cancer cell fate." (PMID 33558529, 2021). "Moreover, high-mobility group protein B1 (HMGB1) is a nuclear protein that is usually released by damaged cells or dead cells or by immune cells and cancer cells." (PMID 33499012, 2021). "Apart from several cancer types with insufficient sample size that were not analyzed, we further found that HMGB1 upregulation was significantly linked with unfavorable RFS of ACC, COAD, PAAD, and READ, but better RFS of LGG." (PMID 34777483, 2021). "It has been demonstrated that high mobility group box 1 (HMGB1), as an essential nuclear and extracellular protein, is a crucial mediator in various pathologic and physiologic situations such as inflammation, immune response, and cancer." (PMID 34456716, 2021).
cancer (continued). "HMGB1 has been reported to participate in inflammation and cancer." (PMID 34867338, 2021). "And once the results hold up, HMGB1 SNP rs1045411 might be used as an index of predicting cancer occurrence in the future." (PMID 33628090, 2021). "Additionally, it was also shown that exosomal HMGB1 play a role in platelet-driven cancer malignancy." (PMID 34721407, 2021). "Moreover, MIR22HG suppresses the proliferation and metastasis of cancer cells also through MIR22HG-derived miR-22-3p targeting high mobility group box 1 (HMGB1) and binding to human gene antigen R (HuR)." (PMID 34638971, 2021). "Thus, immunogenicity of cancer cell deaths in vitro is evaluated by immunostimulatory DAMPs like HMGB1, ATP, CRT, HSP70, HSP90, ANXA1, or cytokines like IFN, CCL2, CXCL1, CXCL10, etc." (PMID 34135914, 2021). "Furthermore, a recent meta-analysis investigated the role of HMGB1 in estimating overall and progression-free survival of patients with diverse cancers." (PMID 33672622, 2021). "Integrating the significance of prognosis, TIICs, ICP genes, and MSI and (or) TMB, we induced that HMGBs might be promising immunological targets for the following cancers: HMGB1 for ACC and KIRC; HMGB2 for ACC and LGG; and HMGB3 for BRAC, SARC, SKCM, and OV." (PMID 34777483, 2021). "In addition, elevated HMGB expression indicated clinicopathological advances in these cancers: HMGB1 in ACC, HNSC, and ESCA; HMGB2 in ACC, HNSC, KIRC, LGG, and LIHC; and HMGB3 in ESCA and HNSC." (PMID 34777483, 2021). "In addition to its nuclear and extracellular roles, cytoplasmic HMGB1 binds many proteins which are involved in cancer progression, autophagy, and is likely involved in the unconventional secretory pathway." (PMID 34805222, 2021). "In addition, they investigated HMGB1 expression in normal and cancer tissues of the breast by Western blot and IHC and observed that HMGB1 expression was significantly higher in cancer tissues than in normal tissues." (PMID 34267603, 2021). "Finally, high mobility group protein B1 (HMGB1) assumes a number of roles in cancer development as well." (PMID 34072546, 2021). "Administration of HMGB1 inhibitors improved outcomes from cancer in several experimental models." (PMID 34943830, 2021). "As an activator of the cancer-immunity cycle, high mobility group box 1 is released simultaneously with cancer antigens to act on TLR2 and TLR4 of DCs to promote DC maturation and induce antitumor immune responses when cancer cells cause immunogenic cell death." (PMID 34071550, 2021). "In addition, TGF-β induces the expression of cysteine-rich 61 (CYR61), connective tissue growth factor (CTGF) and high-mobility group box-1 (HMGB1), which facilitates chemotherapy resistance in cancers by promoting the expression of anti-apoptotic proteins." (PMID 34917620, 2021). "Besides, significant positive correlations between the expression of HMGBs and ICP genes were found in the following cancers: HMGB1 in HNSC, LIHC, PAAD, and PRAD and HMGB2 in HNSC, KIRC, KIRP, LGG, LIHC, PRAD, THCA, and SKCM." (PMID 34777483, 2021). "HMGB1 plays a very important role in division and invasion of cancer cells." (PMID 34646884, 2021). "On the other hand, recent evidence indicated that ferroptotic cancer cells could release signal molecules, including oxidized lipid mediators, eicosanoids, and high mobility group box1 (HMGB1), into the ECM to modulate the anti-cancer immunity." (PMID 34796174, 2021). "We hypothesised that HMGB1 could upregulate galectin-9 expression in cancer cells through the activation of TGF-β production induced in a TLR4-dependent manner." (PMID 34234778, 2021). "This might also be a simple way to explain the strong overexpression of HMGB1 in various cancer types." (PMID 34166567, 2021). "The identification of common interactors of HMGB1 in PC-3 and SKOV-3 cells lines is noteworthy and might suggest that the oncogenic role of HMGB1 overexpression affects basic cellular functions that are altered in different cancers." (PMID 34572914, 2021).
cancer (continued). "The suppressive effect of dipyridamole on cancer cell survival was paralleled by a reduction of HMGB1/receptor for advanced glycation end-products axis, and proliferation- and migration-related β-catenin, Yes-associated protein 1, Runt-related transcription factor 2, and TGF- β1/Smad signals." (PMID 33669632, 2021). "Additionally, CAFs with high ASMA and low high-mobility group box 1 (HMGB1) expression in cancer cells predict OS of invasive ductal BC patients." (PMID 34337083, 2021). "As stated, the HMGB1-RAGE axis in TME is closely associated with carcinogenesis; thus, anti-cancer compounds targeting this axis that possess further anti-inflammatory activity may have far-reaching therapeutic potential." (PMID 33805209, 2021). "Considering the high homology of HMGB2 compared to HMGB1, it might have a similar role in the development of cancer." (PMID 33407071, 2021). "Subsequently, the damage-associated molecular patterns (such as high mobility group box 1, HMGB1) released by cancer cells undergoing ferroptosis may induce cancer cell immunogenicity." (PMID 35174170, 2021). "In cancer, the role of HMGB1 needs further understanding as dual roles of HMGB1 have been reported." (PMID 34721407, 2021). "In this study, we reported that glycation of HMGB1 enhances the cancer-promoting effect of HMGB1." (PMID 34068442, 2021). "We have shown that paclitaxel, an anti-cancer drug, directly causes ROS accumulation and activation of p38MAPK and NF-κB in macrophages, which causes HAT upregulation followed by cytoplasmic translocation and extracellular release of HMGB1." (PMID 32707767, 2020). "While released HMGB1 might likewise contribute to RAGE‐induced muscle atrophy in cancer conditions, HMGB1's ability to activate TLR‐445, 46 limits conclusions about its pro‐cachexia effects via RAGE signalling." (PMID 32159297, 2020). "In addition, Yoon and co-authors have also shown that CAP induced the expression of HMGB1 in cancer cells." (PMID 32698492, 2020). "Scant data are available in regard to the subcellular localization of HMGB1 in malignant tumors." (PMID 33122771, 2020). "Cancer cells undergoing ferroptosis release HMGB1 in an autophagy-dependent manner." (PMID 32778143, 2020). "Similarly, other groups demonstrated that cancer cells of different origin, such as those from malignant mesothelioma, breast, thyroid, and gastric cancers, actively release HMGB1, which promotes their growth." (PMID 33321934, 2020). "HMGB1 was disclosed to be connected with the progression of a variety of cancers." (PMID 32684842, 2020). "Importantly, recent data have demonstrated that DAMPs, and in particular HMGB1, can also be released by cancer cells undergoing immunogenic cell death (ICD) or necroptosis." (PMID 33321934, 2020). "Of note, the HMGB1/TLR2 signaling pathway may trigger a positive feedback loop that fosters cancer resistance to multiple treatments." (PMID 33321934, 2020). "It was reported that HMGB1 played an important role in many diseases, including cancers." (PMID 32684842, 2020). "In contrast, HMGB1 release from dying cancer cells can activate anticancer immunity: the complex of HMGB1 with RAGE or Toll-like receptor 4 (TLR4) triggers cascades of reaction that lead to the local secretion of proinflammatory cytokines, including IL−1, IL−6 and TNF-α." (PMID 32698492, 2020). "Functionally, HMGB1 silencing decreased cancer cell proliferation." (PMID 32328193, 2020). "However, adequately designed prospective, randomized studies in specific patient populations are required to assess the prognostic utility of HMGB1 in various types of cancer." (PMID 32664328, 2020). "We show that cancer cells release HMGB1 upon treatment with TTFields." (PMID 32144446, 2020). "The secreted HMGB1-induced autophagy has been reported to be beneficial for cancer progression." (PMID 32788720, 2020).
cancer (continued). "Increasing recognition of the involvement of HMGB1 in the pathogenesis of various types of cancer has evoked considerable awareness of the potential of this protein to serve as both a prognostic biomarker and therapeutic target in various types of human cancers." (PMID 32664328, 2020). "HMGB1 has been identified as a crucial oncogene in several cancer types." (PMID 33817244, 2020). "It is well known that both radiotherapy and chemotherapy may induce ICD or necroptosis in cancer cells, and therefore increase HMGB1 release in the TME." (PMID 33321934, 2020). "In line with this notion, the knockout of HMGB1 in cancer cells and the antibody-mediated neutralization of TLR4 in the host limit therapeutically relevant immune responses (and hence disease control) driven by anthracyclines, cyclophosphamide, or oxaliplatin in preclinical in vivo models." (PMID 33243969, 2020). "As a significant DAMP, HMGB1 is a key protein required for the immunogenicity of cancer cells." (PMID 32778143, 2020). "This study confirmed that HMGB1 promotes cancer and takes part in cisplatin resistance." (PMID 32328193, 2020). "Furthermore, they depicted that PCCs utilize HMGB1 endogenously as a pro-autophagic protein augmenting cancer cell survival and preventing programmed apoptotic cell death via dislocation of Bcl-2 from Beclin-1." (PMID 32344698, 2020). "Furthermore, light-activated ZHER2:2395-IR700 triggered all hallmarks of immunogenic cell death, as defined by the translocation of calreticulin to the cell surface, and the secretion of ATP, HSP70/90 and HMGB1 from dying cancer cells into the medium." (PMID 33082328, 2020). "Cancer-related elevations in S100B and HMGB1 levels have also been reported." (PMID 33291708, 2020). "HMGB1 is a key molecule that both triggers and sustains inflammation following infection or injury, and is involved in a large number of pathologies, including cancer." (PMID 33324614, 2020). "The study findings reveal an unappreciated molecular mechanism of HMGB1-mediated cisplatin resistance and may provide a new clue in cancer therapy." (PMID 32328193, 2020). "HMGB1 inhibits both apoptosis pathways, thereby enhancing chemoresistance in cancer cells." (PMID 32660524, 2020). "Indeed, autophagy confers drug and irradiation resistance in several types of cancer and, in the meanwhile, it induces the release of additional HMGB1 in the TME, which can further promote autophagy." (PMID 33321934, 2020). "The release of HMGB1 from cancer cells undergoing ICD involves the permeabilization of both the nuclear lamina and the plasma membrane in a two-step process that enables the translocation of the protein from the nucleus to the cytoplasm, followed by its liberation into the extracellular space." (PMID 33243969, 2020). "In conclusion, our results demonstrate that mechanical vibration at 20 Hz promotes the apoptosis of A431 cancer cells, which may be related to changes in the rate of glucose metabolism and/or HMGB1 release by the cells." (PMID 32647502, 2020). "Additionally, in gastric cancer cells, after vincristine, a microtubule-targeting drug treatment, HMGB1 released into the extracellular space to protect cancer cells from apoptosis by upregulating the transcription of Mcl-1." (PMID 32322202, 2020). "Gemcitabine is not considered as an immunogenic chemotherapeutic agent, but could potentiate immune response by stimulating the expression of MHC Class I by cancer cells and it improves release of HMGB1." (PMID 32947882, 2020). "HMGB1, which is the most important member of the high mobility group box protein family, is a nuclear protein with different functions in the cell, since it has a role in cancer progression, angiogenesis, invasion, and metastasis development." (PMID 32973493, 2020). "We hypothesized that CAP-dependent HMGB1 release from dying cancer cells can change the serum HMGB1 level." (PMID 32698492, 2020).